INS (insulin)
Diseases named in the same sentence as INS in open-access papers (continued):
Sharing a sentence is not in itself a finding about the gene and the disease.
breast cancer (continued). "Beyond SHBG, Chen and colleagues found associations between fasting insulin levels and increased risk for breast cancer." (PMID 37377609, 2023). "Given the established role of sustained elevated blood insulin levels in the development of breast cancer, the adverse association of E354Q with breast cancer endpoints suggests that this effect is likely mediated via non-insulinemic pathways." (PMID 37250804, 2023). "Studies showed that elevated insulin levels and hyperinsulinemia are associated with poor prognosis in breast cancer patients." (PMID 36922570, 2023). "In a post hoc analysis, tamoxifen was shown to reduce insulin sensitivity in overweight women at high risk or diagnosed with breast cancer by nearly sevenfold." (PMID 37628874, 2023). "It has previously been demonstrated that women with high levels of insulin are at increased risk of developing breast cancer." (PMID 36920947, 2023). "Both studies suggested that fasting insulin and estradiol explained some of the adiposity–postmenopausal breast cancer association, with fasting insulin having a larger role." (PMID 35048536, 2022). "In cohorts of female breast cancer survivors with assessments of biomarkers up to 1 year postsurgery, higher levels of fasting insulin, compared to lower levels, have been associated with increased recurrences, cancer‐specific deaths, and all‐cause mortality." (PMID 35174651, 2022). "Here, we propose a novel mechanism that oncogenic protein TRIP-Br1 renders breast cancer cells and insulin deficient mice to have higher IR/IGF1R ratio by positively and negatively regulating IR and IGF1R expression at the protein level, respectively." (PMID 35710446, 2022). "In the past few years, many studies have shown that insulin and incretin-based drugs are associated with an increased risk of multiple cancer types, such as pancreatic cancer, breast cancer, and thyroid cancer." (PMID 35933633, 2022). "Other mechanisms of breast cancer risk reduction through physical activity are via reduction in fat, boosting of immune system, and decreased insulin levels in body." (PMID 35366162, 2022). "It is also effective in weight loss, which is indirectly associated with the reduction of breast cancer incidence by lowering insulin levels." (PMID 36575538, 2022). "Inhibiting the protein interactions of this domain has been associated with decreased osteoclastogenesis, increased insulin sensitivity, and reduced breast cancer metastasis." (PMID 35634780, 2022). "Breast cancer risk showed a similar behavior: Adipsin risk, adjusted by insulin and visfatin OR = 56 or HOMA IR and visfatin OR = 22.7." (PMID 35627631, 2022). "Currently the stoichiometric mass action of this pathway remains to be investigated in these breast cancer subtypes, but several studies have linked methionine, mTOR, and insulin signaling pathways, albeit transitively." (PMID 35359364, 2022). "Recently, in a study of the expression of genes related to the insulin and inflammatory pathways in breast cancers, IDE overexpression appears to be a risk factor for relapse and contributes to disease-free survival." (PMID 35406791, 2022). "We reveal that mice with breast cancer driven by mutations upstream of the PI3K/Akt insulin signaling pathway were responsive to dapagliflozin, while those driven by mutations downstream of PI3K/Akt or in pathways with other driver mutations were not." (PMID 35595952, 2022). "A study on overweight and obese women (n = 115) aged 20–69 years with a family history of breast cancer found that the IF diet is superior to the CRD diet with respect to the improvements in insulin sensitivity and the loss of body fat." (PMID 36570146, 2022). "Mice with breast cancer driven by mutations upstream of the PI3K/Akt insulin signaling pathway are found to be responsive to dapagliflozin, while those driven by mutations downstream of PI3K/Akt or in pathways with other driver mutations did not." (PMID 35595952, 2022).
breast cancer (continued). "Among early stage breast cancer patients, elevated levels of fasting insulin are associated with distant recurrence and mortality and while elevated HOMA-IR scores are associated with reductions in breast cancer survival and all-cause survival." (PMID 35241143, 2022). "An insulin signature based on the differential expression of 15 genes has been observed in breast cancer and associated with 8-year disease-free survival." (PMID 35406791, 2022). "The results of this study clearly showed that insulin can cause DOX resistance in MCF-7 breast cancer cell lines." (PMID 34308576, 2021). "A recent prospective long-term breast cancer study found that perioperative high intake of glucose was not only associated with high insulin blood levels but also with an extremely poor prognosis." (PMID 34993132, 2021). "The effect of high insulin levels on tumors is reflected not only in breast cancer, but is also a risk factor for pancreatic cancer." (PMID 34485124, 2021). "Further, high fasting insulin levels are associated with poorer outcomes for women with early breast cancer." (PMID 34440224, 2021). "Chronically increased insulin levels have been associated with cancers of breast, colon, pancreas, and endometrium." (PMID 33693438, 2021). "Nevertheless, the detailed mechanisms underlying how Hes and CA modulate the insulin pathway in a breast cancer cell are worthy of investigation." (PMID 34575098, 2021). "The Prospective Women’s Health Study measured serial insulin levels over a six-year period and showed a two-fold increased risk of breast cancer in subjects with insulin levels in the top tertile compared with the bottom." (PMID 34360563, 2021). "The insulin-resistant and reproductive clusters are associated with breast cancer at nominal significance (p < 0.05)." (PMID 34207127, 2021). "Apart from insulin itself, several other nodes from insulin signaling have been implicated in breast cancer." (PMID 34225729, 2021). "An increased fasting insulin level will increase the risk of breast cancer, and a higher insulin level can promote breast cancer growth and metastasis through the PI3K/AKT signaling pathway, and promote tumor progression." (PMID 34485124, 2021). "The improved systemic adipocytokine profile (increased adiponectin:leptin ratio, increased omentin, decreased insulin) observed after only 12 weeks has implications for breast cancer risk and recurrence." (PMID 34638355, 2021). "It has been indicated that insulin signaling pathway activation was associated with increased risk of breast cancer and colorectal cancer." (PMID 35372372, 2021). "Antiestrogen activity of SERMs increases T2DM risk in breast cancer patients as insulin homeostasis is regulated in an estrogen-dependent manner." (PMID 34577625, 2021). "High body mass index (BMI) is correlated with an increased production of hormones (estrogens, insulin, testosterone, leptin), and pro-inflammatory cytokines, which have been associated with breast cancer (BC) risk and recurrence." (PMID 34771702, 2021). "Few studies have shown that serum C-peptide level is associated with increased risk of breast cancer, and C-peptide has only been assessed as a marker for pancreatic insulin secretion." (PMID 33180852, 2020). "We also identified enriched pathways in genes regulated by differentially expressed 42 miRNAs, which include signaling associated with breast cancer, energy metabolism, glucose metabolism, and insulin." (PMID 32466456, 2020). "Previously, it was shown that continual administration of insulin over ≥ 3 years was associated with an increased risk of mortality in breast cancer." (PMID 35582045, 2020). "Long-term use of insulin analogs, insulin glargine, is associated with an increased risk of breast cancer in women with T2DM." (PMID 32631390, 2020). "Circulating C-peptide, and insulin levels have been associated with increased breast cancer risk and cancer-specific mortality, even after adjustment for adiposity." (PMID 33604295, 2020).
breast cancer (continued). "Several studies have shown that elevated plasma insulin levels are associated with an increased incidence of various cancers and higher recurrence in breast cancer survivors." (PMID 33108715, 2020). "Interactions between IGF1 and insulin on all-cause mortality, breast cancer-specific mortality, and breast cancer recurrencea." (PMID 32974138, 2020). "High body fat levels correlated with fasting insulin, leptin, triglycerides and inflammatory markers (IL-6, C-reactive protein), and increased breast cancer risk in postmenopausal women with normal BMI." (PMID 33604295, 2020). "Insulin resistant states, such as metabolic syndrome and type-2 diabetes, are strong risk factors for breast cancer in women." (PMID 32774370, 2020). "Dysregulation of PI3K/AKT/mTOR-signaling is a regulator of aerobic glycolysis and provides scientific rational for controlling insulin-activation of PI3K/AKT/mTOR in both women with breast cancer and at-risk women." (PMID 32153503, 2020). "Previous studies for circulating glycemic traits (GTs), including fasting glucose (FG) and insulin (FI) concentrations, have shown inconsistent associations with breast cancer development." (PMID 33193614, 2020). "A clinical investigation also indicated that fasting serum insulin is an independent risk factor for benign proliferative breast disease which is associated with early stages of breast cancer development." (PMID 32631390, 2020). "The risks associated with breast cancer include the activation of the insulin pathway, activation of the IGF pathway, and regulation of endogenous sex hormones." (PMID 32528752, 2020). "Obese women with mammary cancer also show a marked deregulation of insulin signaling, which causes an imbalance in cell proliferation, differentiation, apoptosis, altered expression of adipocytokines and C-reactive protein (CRP)." (PMID 32903534, 2020). "Higher levels of leptin caused by insulin secretion lead to the creation of an autocrine feedback loop which increases mitogenesis and decreases apoptosis in breast cancer cells." (PMID 32824813, 2020). "High insulin levels were reported in obese patients, and obesity is known to be associated with many cancer types including breast cancer." (PMID 32133259, 2020). "The proliferation and spread of breast cancer is intimately linked to cellular glucose metabolism, given that glucose is an essential cellular metabolic substrate and that insulin signalling has mitogenic effects." (PMID 31360518, 2019). "Elevated nonfasting C-peptide levels, a surrogate marker for pancreatic insulin secretion, were associated with a higher breast cancer risk among women above 60 years of age within the EPIC (European Prospective Investigation into Cancer and Nutrition) study." (PMID 30634494, 2019). "Use of insulin (HR 1.18, 95% CI 1.03–1.36) was associated with a slightly increased incidence of breast cancer." (PMID 30895533, 2019). "In one study, the use of metformin was reported to be associated with an increased risk of breast cancer among insulin users." (PMID 30895533, 2019). "Insulin is a growth factor that increases proliferation and decreases apoptosis, and elevated levels of insulin are associated with different cancers, including breast cancer." (PMID 31703648, 2019). "Insulin stimulates the production of T, which can account for higher T levels ‘associated’ with breast cancer." (PMID 31888528, 2019). "On the other hand, high levels of circulating insulin as well using insulin and insulin analogues to control blood glucose levels were associated to an increased risk of breast cancer." (PMID 31835318, 2019). "Insulin levels were significantly associated with increased breast cancer risk in a large prospective cohort of postmenopausal women." (PMID 30634494, 2019). "High insulin levels are positively associated with an increased breast cancer risk in post-menopausal women." (PMID 31555644, 2019).
breast cancer (continued). "In contrast, 2-hour glucose levels are associated with a greater risk of breast cancer, reflecting beta cell function and skeletal muscle insulin sensitivity, thus representing relatively long-term exposure to IR." (PMID 31246991, 2019). "In our hands, however, breast cancer xenografts harboring the insulin-unresponsive, DR-resistant, PIK3CA-activating mutation H1047R remained largely sensitive to the anti-tumoral effects of metformin." (PMID 30984619, 2019). "A positive trend in breast cancer risk was observed with increasing cumulative use of insulin, the estimate being 1.46 (95% CI 1.19–1.81) for the amount of DDDs being 1200 or more when compared with no use at any time." (PMID 30895533, 2019). "Higher serum insulin levels have been found to be associated with an increased breast cancer risk in several epidemiological studies." (PMID 30241536, 2018). "Observational studies and randomized clinical trials are limited in their ability to investigate associations of long-term insulin exposure with relatively rare outcomes such as breast cancer." (PMID 30092829, 2018). "Adipose-derived metabolic hormones, such as the adipokines leptin and adiponectin, modulate insulin sensitivity, activate NFkB and the mTOR pathway and are also associated with breast cancer risk." (PMID 29587682, 2018). "Research is needed to identify if changes in insulin pathways or other biomarkers translate into improved survival and to identify effective weight loss interventions for breast cancer survivors who have difficulty losing weight." (PMID 29587682, 2018). "Long-term insulin exposure has been implicated in breast cancer etiology, but epidemiological evidence remains inconclusive." (PMID 30092829, 2018). "Higher levels of circulating insulin increase the bioavailability of estrogen, a process associated with a poorer prognosis in breast cancer patients." (PMID 29804217, 2018). "Positive changes in insulin-related parameters have been identified with weight loss interventions provided to breast cancer survivors." (PMID 29587682, 2018). "Significant improvement in both parameters suggests that breast cancer survivors with greater weight loss are exposed to less circulating insulin." (PMID 29587682, 2018). "Obesity and body composition are also associated with breast cancer by increasing the levels of estrogen, proinflammatory cytokines, insulin resistance, and breast density." (PMID 30112392, 2018). "Epidemiologic evidence identifies a two-fold increase in the risk of breast cancer recurrence and a three-fold increased risk of death in breast cancer survivors with the highest fasting insulin levels." (PMID 29587682, 2018). "Increased levels of fasting insulin and insulin-like growth factors have been associated with distant recurrence and death in breast cancer survivors." (PMID 28702218, 2018). "On the other hand, metformin, commonly prescribed used oral antidiabetic regimen, which increases insulin sensitivity and improves glycemic control, has been found to reduce breast cancer risk." (PMID 27832382, 2017). "The association is particularly strong in postmenopausal women, in whom high insulin levels have been associated with a twofold increase in breast cancer risk." (PMID 28446149, 2017). "Recent studies in postmenopausal obese women and in obese and overweight breast cancer survivors following treatment suggest that weight loss decreases serum levels of leptin, insulin, and estrogens, and Ki67 expression in normal breast epithelial cells." (PMID 29187227, 2017). "Studies showed that genetic variants in SELENOP were associated with the risk of breast cancer, prostate cancer, advanced colorectal adenoma and colorectal cancer as well as first phase insulin response and the occurrence of abdominal aortic aneurysm." (PMID 28499373, 2017).
breast cancer (continued). "It has been proposed that high BMI is connected to increased insulin and insulin-like growth factors, which in turn contribute to the elevated risk of breast cancer." (PMID 29228605, 2017). "In the case of breast cancers, insulin levels are associated with disease stage and have recently been shown to provide prognostic information to improve breast cancer detection and management." (PMID 28717385, 2017). "There has been one finding of a CREB-PPP1R1C gene fusion associated with enrichment of insulin signaling pathway genes in breast cancer." (PMID 29383111, 2017). "Reported data represents the observed association between use of insulin secretagogues preceding breast cancer and the inflammatory C–C chemokine profiles at the time of cancer diagnosis in women with diabetes mellitus." (PMID 28275673, 2017). "Earlier studies have shown that insulin, a debated risk factor for breast cancer, can stimulate cell proliferation in human breast cancer cell lines and also in normal breast tissue." (PMID 27832382, 2017). "Obesity, on the other hand, which increases the risk of postmenopausal breast cancer, likely via insulin as a mediator, decreases MD." (PMID 27832382, 2017). "We recently reported that interleukin-6 (IL-6), an inflammatory marker associated with breast pathology and the development of breast cancer, decreases with diet intervention and weight loss in both insulin-sensitive and insulin-resistant obese women." (PMID 28555011, 2017). "High circulating insulin increases risk of breast cancer recurrence (comparison of highest to lowest quartile, HR = 2.0 (95% CI, 1.2–3.3))." (PMID 27338371, 2016). "The protein encoded by IGF1 gene is similar to insulin, in function and structure and belong to a family of proteins involved in mediating growth and development of breast cancer." (PMID 27152840, 2016). "This study evaluated the association between four commonly used drugs, metformin, insulin, statins, and levothyroxine, and breast cancer." (PMID 27648070, 2016). "High body mass index (BMI) results in an increased production of hormones (estrogens, insulin, leptin), and pro-inflammatory cytokines, which have, in turn, been associated with breast cancer risk." (PMID 27464488, 2016). "In some other studies, insulin use also increased the risk of some types of cancer, including non-Hodgkin’s lymphoma, breast cancer and colorectal and liver cancer." (PMID 27906989, 2016). "Consistent with this premise, risk for breast cancer is increased in association with higher circulating levels of insulin and IGF-1." (PMID 27338371, 2016). "The aim of this study was to evaluate the association of metformin, insulin, statins, and levothyroxine and breast cancer characteristics and outcome." (PMID 27648070, 2016). "Human insulin, especially NPH, was often used as exposure comparison group in the studies that investigated risk of breast cancer related to insulin analogue use." (PMID 26242987, 2015). "Another study revealed that the risk of breast cancer increased in the first 3 years after the start of insulin glargine use, after which the risk of breast cancer remained at the same level." (PMID 26242987, 2015). "In fact, several prospective studies have demonstrated strong positive associations between different measures of insulin signaling and a poor breast cancer prognosis, including an increased risk of distant recurrence and mortality." (PMID 26029167, 2015). "Considering that cancer is a heterogeneous disease with different aetiologies, and breast cancer being the most common female cancer, we focussed this review on the association of exogenous insulin (analogue) exposure and the risk of breast cancer." (PMID 26242987, 2015). "Model III suggested that human insulin users who also had been treated with statin for as short as <2 years had a significantly lower risk of breast cancer." (PMID 26537234, 2015).